TLR7 (toll like receptor 7)
Diseases named in the same sentence as TLR7 in open-access papers (continued):
Sharing a sentence is not in itself a finding about the gene and the disease.
tumor (continued). "Consistently, exogenous dsRNA participates in driving Type I IFN induction via targeting RNA-sensing PRR pathways, including RIG-I/MDA5-IPS-1, TLR7-MyD88 and TLR3-TICAM-1 in dendritic cell subset, so as to evoke and amplify CD8+ T cell anti-tumor immunity." (PMID 37138885, 2023). "In GI tumors, both TLR7 and TLR8 agonists in combination with RT showed a significant decrease in tumor growth." (PMID 37112730, 2023). "TLR7 stimulation leads to decreased expression of CD200R in immunoinfiltrating cells (CD45+), resulting in anti-tumor effects in multiple tumors." (PMID 37511958, 2023). "TLR9 activation is similar to TLR3/ TLR7/TLR8 activation and results in increased expression levels of costimulatory molecules such as TRAIL, which can induce tumor cell death, and CCR7, which promotes trafficking of APCs to lymph nodes." (PMID 37112730, 2023). "Among TLR7-positive patients, those with the highest CD3–CD8 tumor–stroma index had a five-year DSS of 87.9% (95% CI 76.7–99.1) compared to 48.0% (95% CI 37.4–58.6; p < 0.001, log-rank test) among patients with the lowest CD3–CD8 tumor–stroma index." (PMID 36649244, 2023). "Our recent study showed that a hydrogel co-loaded with the TLR7 agonists imiquimod and ropivacaine increased the infiltration of CD8+T cells into the residual tumor tissues to prevent tumor recurrence." (PMID 38041074, 2023). "Tumor‐secreted microRNAs bind to murine TLR7 and human TLR8 in immune cells to trigger tumor metastasis." (PMID 37254712, 2023). "Since it is reported that the anti-tumor effect of the TLR7 agonist imiquimod is CD8+ T cell dependent, we showed that DSP-0509 has the same mechanism of anti-tumor activity." (PMID 36793737, 2023). "Accordingly, numerous clinical trials highlighted that TLR-7/9 agonists administration, individually or in combination with ICB therapies, has the potential to stimulate specific T cell response and subsequent tumor regression, even for patients with MM." (PMID 38239354, 2023). "Among all TLR2, TLR4, and TLR5 subgroups and the positive TLR7 subgroup, patients with a low CD3–CD8 tumor–stroma index exhibited a worse survival." (PMID 36649244, 2023). "Based on the preliminary data available, TLR7 and TLR9 agonists currently in development suggest anti-tumor activity when used as monotherapy or in combination with approved immune checkpoint inhibitors." (PMID 36890302, 2023). "We finally demonstrate that delivery of a TLR7 agonist to Tregs in the TME can reprogram the TME to a less immunosuppressive state, leading to significantly reduced tumor growth and enhanced mouse survival." (PMID 37928524, 2023). "R848 (TLR7/8 agonist), and lefitolimod (TLR9 agonist) have been found to transform TAMs to M1 macrophages and limit tumor progression." (PMID 37720226, 2023). "Quantitative real‐time PCR analyses showed that TLR7 was highly expressed at the mRNA level in short‐term cultures from both, human (LON560) as well as murine (KC623) PDAC tumor cells." (PMID 36602302, 2023). "Some Toll‐like receptor ligands, such as imiquimod, a TLR7 agonist, and CpG, a TLR9 ligand, can directly induce apoptosis of TLR positive tumor cells, or enhance tumor‐infiltrating innate immune cells and tumor specific T‐cell functions." (PMID 38063246, 2023). "Other TLR7 specific agonists include 3M-052, 3M-011, DSR-6434, and SZU-101, all showing anti-tumor activity in human cancer models." (PMID 36672572, 2022). "TLR7 agonists in combination with checkpoint inhibitors targeting PD-1 and CTLA-4 have been shown to be safe and effective in immunotherapy-resistant tumor models to promote more long-term immune responses." (PMID 36389785, 2022). "Both IMQ and RSQ can promote tumor regression through the activation of immune responses by acting as agonists for TLR-7 and TLR-7/TLR-8, respectively." (PMID 36297510, 2022).
tumor (continued). "Recently, another synthesized ODN-based TLR7/9 antagonist HJ901 was shown to significantly inhibit tumor cell proliferation and tumor growth in cell lines or animal models carrying the MyD88 L265P mutation." (PMID 36479129, 2022). "Lung tumor cell-derived exosomes can transfer miR-21/29a to activate TLR7 and TLR8 in immune cells, which were promoted to tumor development and metastasis." (PMID 35711455, 2022). "Inhibition of TLR7 and TLR9 reduces human cholangiocarcinoma cells’ proliferation and tumor development." (PMID 36476317, 2022). "The Croce group first identified tumor-secreted miR-21 and miR-29a as ligands that bind to TLR7 and TLR8 of immune cells, triggering a pro-metastatic inflammatory response and changing the microenvironment of tumor growth or metastasis." (PMID 35637969, 2022). "High expression of TLR7/TLR8 in lung cancer cells has been accompanied by resistance to apoptosis induced by chemotherapy and increased tumor cell survival." (PMID 36613950, 2022). "On the other hand, TLR7 stimulation promoted immune cell infiltration in TME, which functioned as a tumor suppressor." (PMID 35413927, 2022). "MEDI9197 (3M-052), a novel designed lipophilic TLR7/8 agonist, is found to regulate the enrichment and activation of CD8+ T cells and NK cells, polarization of Th1 cells and inhibition of tumor growth in multiple syngeneic models." (PMID 35413927, 2022). "Single IT administration of soluble resiquimod was compared to TransCon TLR7/8 Agonist containing an equivalent dose of soluble resiquimod in CT26 tumor-bearing mice and tumor growth inhibition and systemic cytokine induction were assessed." (PMID 36123697, 2022). "Dendritic cells stimulated with TLR3 and TLR7 agonists were found to upregulate ERK signaling, likely contributing to the enhanced dendritic cell activation and anti-tumor T-cell responses observed in CT26 tumors." (PMID 35740589, 2022). "Tumor growth was significantly inhibited at all dose levels, consistent with previous dose titration experiments showing TransCon TLR7/8 Agonist inhibited CT26 and MC38 tumor growth in a dose-dependent manner." (PMID 36123697, 2022). "Previous studies have shown that multiple PRRs (TLR2, TLR3, TLR4, TLR7, TLR8 and RIG‐1) in stromal cells recognise tumour cell‐derived EVs and participate in tumour metastasis." (PMID 36068649, 2022). "It's worth noting that TLR1, TLR2, TLR3, TLR7, TLR8, and TLR9 were adversely connected with RNAss in the majority of cancers, but favourably correlated with RNAss in a very small number of tumours (KIRC, MESO, LAML, CHOL, KICH and THYM)." (PMID 35801728, 2022). "TLR3, TLR4 and TLR7 are upregulated in certain types of tumour cells, and their expression patterns are associated with tumour progression, suggesting that the innate immunity‐related factors may function as tumour promotors rather than suppressor." (PMID 35050535, 2022). "We stained paraffin‐embedded sections of 100 CLL‐infiltrated and 100 tumour‐free lymph nodes for pSTAT6, an essential downstream target of IL4, and pIRAK4, a downstream target of TLR7/8/9." (PMID 35959629, 2022). "Importantly, combination treatment with TransCon TLR7/8 Agonist and anti-PD1 antibody yielded greater anti-tumor activity over either agent alone, suggesting that T cell promoting immunotherapies may further potentiate anti-tumor responses in TransCon TLR7/8 Agonist treated tumors." (PMID 36123697, 2022). "This engineered virotherapy has also been applied to autologous tumor vaccines including GVAX (GM-CSF), FVAX (FLT3L), and TEGVAX (GM-CSF, TLR4 agonist, and TLR7/8 agonist)." (PMID 36031601, 2022). "On the other hand, treatment with certain adjuvants, such as TLR7/8 or STING agonist, did result in effective tumor growth inhibition." (PMID 35890247, 2022). "Studies have shown that TLRs located in cells (TLR3, TLR7, TLR8, or TLR9) are more effective in triggering anti-tumor immune responses than extracellular TLRs (TLR1, TLR2, TLR4, or TLR6)." (PMID 35965509, 2022).
tumor (continued). "In the present study, we constructed a novel tumor vaccine (SZU251 + MUC1 + Al) containing MUC1 and two types of adjuvants: a TLR7 agonist (SZU251) and an aluminum adjuvant (Al)." (PMID 36499455, 2022). "A combined administration of TLR7 and TLR9 agonists with PD-1 blockade in head and NSCC suppresses tumor growth with an abscopal effect observed related to TAM and CD8+ T cells activation." (PMID 36230990, 2022). "Herein, we decided to investigate the role of four different MyD88-dependent single TLRs (TLR2−/−, TLR4−/−, TLR7−/− and TLR9−/−) in BCG tumor treatment." (PMID 34341449, 2021). "TLR7 and TLR8 activation led to the reprogramming of tumor promoting M2 TAM phenotype to antitumor M1 phenotype." (PMID 33572196, 2021). "Other studies showed microbiota-induced activation of TLR4 and TLR7 resulting in pro-tumorigenic immunosuppressive TME in early and progredient tumor stages TLR5 has been described to be upregulated in TME macrophages, and to be related to tumor growth." (PMID 34298645, 2021). "TLR7 mRNA relative level in CD8+ T cells from GC patients (both peripheral and tumor-infiltrating) was approximate twofold reduced in comparison with that in CD8+ T cells from NCs (LSD-t test, P < 0.05)." (PMID 34620075, 2021). "At the cellular level, USP18, TLR7, IL21R, GCNT1 and CHST7 were expressed in various tumor cell lines, while the expression of LHX2, IL2RA and IL5RA was low in CCLE." (PMID 34001679, 2021). "TLR7/8 PLGA-based vaccine formulations have also been studied in the context of mucosal and tumor immunizations." (PMID 34058283, 2021). "We evaluate BCG intratumoral treatment in a subcutaneous MB49 tumor model using different knockout (KO) mice (STING−/−, cGAS−/−, TLR2−/−, TLR3−/−, TLR4−/−, TLR7−/−, TLR9−/−, TLR3/7/9−/−, MyD88−/−, IL-1R−/−, Caspase1/11−/−, Gasdermin-D−/− and IFNAR−/−)." (PMID 34341449, 2021). "The six genes belonged to different functional groups: antigen presentation (HLA-DPA1 and CD1C), innate immune response (TLR7), type II interferon signaling (IFNB1), tumor marker (MMP2), and proliferation marker (MKI67)." (PMID 34209514, 2021). "A very recent study highlights the strong antitumor activity of resiquimod (TLR7 agonist, analogue to imiquimod) in NSCLC due to its effects of immuno-modulation of the tumor microenvironment." (PMID 33578955, 2021). "The expression of TLR1, TLR3, TLR5, TLR6, TLR7, TLR8, and TLR10 show significantly decreasing trends from normal tissues to surrounding tumor tissues and to tumor tissues." (PMID 34141706, 2021). "Based on this property of TLRs, TLR agonists, such as TLR4, TLR7/8 and TLR9, are currently tested in cancer research with some success in stimulating TAM polarization into an anti-tumor phenotype." (PMID 34178692, 2021). "Another study has shown significant tumor suppression and synergistic IFN-γ secretion by TLR7/8/9 combination treatments." (PMID 34959344, 2021). "Herein, we investigate the effect of BCG tumor treatment in TLR2−/−, TLR4−/−, TLR7−/− and TLR9−/− mice." (PMID 34341449, 2021). "LCCDEs miR-21 and miR-29a can activate Toll-like receptors 7 (TLR7) and 8 (TLR8) on immune cells to activate NFκB and prometastatic inflammatory response, ultimately leading to tumor growth and metastasis." (PMID 33504342, 2021). "The six genes of the signature belonged to different functional immune-related groups: antigen presentation (HLA-DPA1 and CD1C), innate immune response (TLR7), type II interferon signaling (IFNB1), tumor marker (MMP2), and proliferation marker (MKI67)." (PMID 34209514, 2021). "Delivery of the TLR7/8 agonist-loaded NPs results in enhanced ADCC with cetuximab antibody and increases its antitumor efficacy in mice tumor model." (PMID 33409265, 2020). "In the present study, we treated AML tumor cells with DAC, and conjugated a new TLR7 agonist SZU-106, which is derived from the previous synthesized drug SZU-101, to the DAC treated cells." (PMID 32922200, 2020).
tumor (continued). "SC1 treatment reportedly activated NK cells in a TLR7- and IFN-α-dependent manner, and SC1 thus reverses NK cell anergy leading to efficient tumor cell lysis." (PMID 32377528, 2020). "The combination with activating TLR7 and inhibiting TGF-β signaling can reprogram TAMs to the M1 phenotype, which can enhance the tumoricidal activity of TAMs and reduce tumor progression." (PMID 33224886, 2020). "Altogether, these results indicate that the activation of TLR7, TLR8, and TLR9 of TAMs can change macrophages from a tumor-promoting effect to an anti-tumor effect." (PMID 33224886, 2020). "Like TLR7/8 agonists, TLR9 agonists and STING agonists delivered IT also promote anti-tumor immunity in mouse models, and are currently being investigated in clinical trials (NCT02675439, NCT03172936, NCT02254772)." (PMID 31511088, 2019). "TLR7/8 agonists (imidazoquinolines), TLR9 agonists (synthetic CpG oligonucleotides) and STING agonists (cyclic di-nucleotides) have all shown potent anti-tumor activity in a range of murine cancer models." (PMID 31511088, 2019). "Activation of DC via TLR7 leads to increased IFN-I signaling as well as enhanced antigen presentation and T cell priming within the tumor." (PMID 30979057, 2019). "Combination activity of TLR7/8 agonism with immunotherapies was assessed in vitro by human DC-T cell MLR assay, and in vivo using multiple syngeneic mouse tumor models." (PMID 31511088, 2019). "As expected, ssRNA and dual-function vector therapy significantly promoted the expression of TLR7 and the phosphorylation of IRF3 and NF-κB in tumor tissues." (PMID 31849942, 2019). "In another study, NFκB in macrophages was activated through binding of miR-21 and miR-29a, secreted by tumor-derived exosomes, to murine TLR7 and human TLR8, to trigger a TLR-mediated pro-metastatic inflammatory response to promote tumor growth and metastasis." (PMID 31555295, 2019). "Contrary to the results in TLR7-sufficient mice, KxPxCx-engrafted TLR7KO mice treated with R848 experienced increased tumor growth relative to vehicle-treated mice." (PMID 31615993, 2019). "In a syngeneic mouse model of colon cancer, treatment with combined TLR7/8 and 9 agonists significantly reduced the number of MDSC as well as increased the number of NK and CD8+ T-cells infiltrating the tumor site." (PMID 31695691, 2019). "There is evidence that IFN can also repolarize neutrophils and macrophages to an anti-tumor phenotype, which is in agreement with observations made for MDSC in terms of TLR7/8- and TLR9-targeted therapies." (PMID 31694706, 2019). "In our whole population-based study of NPC in Finland, we examined the expression of TLR1, TLR2, TLR4, TLR5, TLR7, and TLR9 in 150 tumours and analysed their pattern of expression according to EBV and HPV status, and clinical outcome." (PMID 31238894, 2019). "This localized TLR7/8 agonism leads to Th1 polarization, enrichment and activation of natural killer (NK) and CD8+ T cells, and inhibition of tumor growth in multiple syngeneic models." (PMID 31511088, 2019). "It was represented that tumor-released miRNAs act as a ligand for TLR family, human TLR8, and murine TLR7 in immune cells that promote pro-metastatic inflammatory factors and eventually results in tumor cell movement and aggressiveness." (PMID 31291956, 2019). "It has been reported that TLR7 agonist 852A can stimulate pDCs to secrete abundant type I IFN and thus inhibit the proliferation of tumor cells." (PMID 31849942, 2019). "Another TLR7 agonist, 852A was found to stimulate plasmacytoid DCs to produce IFN type I and activate both CD8+ T cells and NK cells resulting in anti-tumor response." (PMID 30976817, 2019). "It was reported that miR-21 induces inflammatory responses in macrophages by binding to murine TLR7 and human TLR8, and then triggers a TLR-mediated prometastatic inflammatory response, likely leading to tumor growth and metastasis." (PMID 29892301, 2018).
tumor (continued). "Therein, mRNA activates toll like receptor 7 (TLR7) on plasmacytoid dendritic cells for the production of type I interferon and induction of robust anti-tumor activity." (PMID 30249040, 2018). "Intratumoral injections of TLR7 and TLR9 agonists [1V270 and SD-101(CpG), respectively] alongside with systemic administration of anti-PD-1 mAbs successfully suppressed tumor growth in murine models of head and neck squamous cell carcinoma." (PMID 30349530, 2018). "Tumor-secreted miRNAs (miR-21 and miR-29a) can function as ligands, binding to the receptors of the Toll-like receptor (TLR) family, namely, murine TLR7 and human TLR8." (PMID 28523250, 2017). "pDCs play an essential role by recognizing foreign pathogens and tumor cells through a panel of pattern recognition receptors (PRR), particularly toll-like receptor 7 (TLR7)." (PMID 27588480, 2016). "Taken together these data suggest that RT can modulate the phenotype of response generated by TLR7 agonist-mediated immune activation possibly through the provision and uptake of TAAs by APC, subsequent to RT-induced tumor cell death." (PMID 26959743, 2016). "In summary, this study describes the novel TLR7 agonist DSR-29133 which is well tolerated when administered systemically and leads to acute immune activation and anti-tumor activity when administered as a monotherapy." (PMID 26959743, 2016). "Tumor growth in vivo was found to be enhanced when compared to controls with empty vector PANC1 cells (TLR7+ and TLR8+, each n=5 vs. empty vector, n=4)." (PMID 26134824, 2015). "In summary, we synthesized a novel TLR7 agonist and conjugated with stemness antigen OCT4 to develop a safe and effective immunotherapeutic tumor vaccine." (PMID 25990580, 2015). "At a concentration of 100 μmol/l of 5-FU relative cell viability of TLR7+ and TLR8+ PANC1 tumor cells was less reduced when compared with empty vector PANC1 tumor cells (62 and 73% vs. 58% for empty vector cells; P<0.05 and P<0.0001)." (PMID 26134824, 2015). "For in vitro/in vivo studies TLR7/TLR8 overexpressing PANC1 cell lines were generated and analyzed for effects of (un-)stimulated TLR expression on tumor cell proliferation and chemoresistance." (PMID 26134824, 2015). "Untreated TLR7+ and TLR8+ PANC1 cells showed significantly increased tumor cell proliferation when compared to controls at 72 h after seeding (TLR7, 181% and TLR8, 182% vs. empty vector, 153%; P<0.002 and P<0.005)." (PMID 26134824, 2015). "CC lines significantly increased MFI of TLR-3 and TLR-7 in comparison with the LPS group, whereas, for TLR-9, only tumor cells infected with viruses HeLa and SiHa, induced an increase in MFI (P < 0.05)." (PMID 25309919, 2014). "The TLR7/8 agonist 3M-052 and the TLR9 agonist CpG ODN both trigger innate immune responses that support the induction of tumor-specific immunity." (PMID 24982761, 2014). "Topical administration of Imiquimod, the ligand for TLR7, resolves skin manifestations in CLL patients and increased expression of co-stimulatory molecules on leukemic tumor cells." (PMID 25112836, 2014). "IMQ is a potent toll-like receptor-7 (TLR7) stimulator with anti-tumor properties; most importantly, it promotes DC maturation and activation to aid cross-priming of CD8 T cell responses to tumor antigens." (PMID 25518732, 2014). "Tumor stromal pathways are also in evidence with the common genes including; TLR4, TLR7, HLA-DRA, HLA-DQA1, CXCR4, FOS and TGFB2 (immune surveillance and chemokine pathways) and NF2, ITGA7, PGF, ITGA4, PDGFD and PARVA (focal adhesion)." (PMID 23226201, 2012). "A previous study also showed that treatment of RMA-S tumor-bearing mice with a small molecule agonist for TLR7 named SC1 did not result in an increase in NK cell number but induced significant NK cell activation." (PMID 41597427, 2026).